CFDP1 (chromatin remodeling protein CFDP1)
Description:
Required for the structural stability of pericentromeric heterochromatin. Regulates heterochromatin state by stabilizing CBX5/HP1alpha and H3K9me3 at major satellites and CENPA at minor satellites and is required for incorporation of histone H2AZ1/H2AZ into chromatin (By similarity). Maintenance of chromatin structure promotes binding of guanine-nucleotide releasing factor RCC1 to minor and major satellite repeats (By similarity). Chromatin-bound RCC1 maintains high levels of GTP-bound RAN near the centromeric heterochromatin, facilitating RAN-mediated microtubule nucleation during mitosis (By similarity). Plays a role in craniofacial development (By similarity). Required to maintain normal cell function in embryonic development (By similarity).
Synonyms: BCNT; CENP-29; p97; CP27; SWC5; Yeti; BUCENTAUR
Tractability: PROTAC: UniProt records ubiquitination sites on it; ubiquitination databases record sites on it; its protein half-life has been measured.
Gene: Protein-coding gene on chromosome 16 (75,293,698 to 75,433,503, reverse strand). Ensembl gene ENSG00000153774.
Subcellular location: Chromosome, centromere, kinetochore; Nucleus; Chromosome
Subcellular location (Human Protein Atlas): Nucleoplasm; Vesicles
Gene Ontology:
Biological process: chromatin remodeling
Cellular component: chromosome; nucleus; Swr1 complex
Genetic constraint (gnomAD): Loss-of-function variants: 27 observed, 33.86 expected, observed/expected ratio (o/e) 0.8, 90% interval 0.59 to 1.1. The synonymous counts are far from expectation, so gnomAD's model fits this gene poorly and the ratio says little. Missense variants: 376 observed, 310.19 expected, observed/expected ratio (o/e) 1.21, 90% interval 1.11 to 1.32. Synonymous variants: 149 observed, 106.76 expected, observed/expected ratio (o/e) 1.4, 90% interval 1.22 to 1.6.
Homologues: Orthologues: chimpanzee CFDP1 (99% identical), pig CFDP1 (96% identical), rabbit CFDP1 (93% identical), macaque CFDP1 (91% identical), guinea pig CFDP1 (88% identical), mouse Cfdp1 (83% identical), rat Cfdp1 (77% identical), tropical clawed frog cfdp1 (57% identical), zebrafish cfdp1 (49% identical).
Diseases named in the same sentence as CFDP1 in open-access papers:
CFDP1 is named in the same sentence as 26 diseases in open-access papers, as found by Europe PMC text mining. Sharing a sentence is not in itself a finding about the gene and the disease. The quoted sentences say what the papers report.
hepatocellular carcinoma (3 papers, 2023 to 2024). A malignant tumor that arises from hepatocytes. "In contrast, in hepatocellular carcinoma, CFDP1 overexpression was associated with shorter OS (hazard ratio: 2, p = 0.012) and DFS (hazard ratio: 1.8, p = 0.0099), promoting cancer progression by activating the NEDD4/PTEN/PI3K/AKT signaling pathway." (PMID 38893126, 2024). "Nonetheless, the underlying mechanisms associated with CFDP1 that contribute to hepatocellular carcinoma (HCC) and the specific biological role of CFDP1 remain vague." (PMID 35861040, 2023).
heart failure (2 papers, 2022 to 2023). Inability of the heart to pump blood at an adequate rate to meet tissue metabolic requirements. "Further genes upregulated in cardiac art ECs in obesity, including Hivep2 and Cfdp1, were associated with atherosclerosis, while CDKN1A, the gene encoding the senescence factor p21, was associated with heart failure." (PMID 36400935, 2022).
migraine (2 papers, 2022 to 2025). "Cross-trait gene-based overlap analysis identified 33 genes significantly associated (Pgene-based < 3.85 × 10−6) with migraine and T2D, and 11 genes associated with headache and T2D, with 7 genes (EHMT2, SLC44A4, PLEKHA1, CFDP1, TMEM170A, CHST6, and BCAR1) common between them." (PMID 36292730, 2022). "Notably, seven of these genes (EHMT2, SLC44A4, PLEKHA1, CFDP1, TMEM170A, CHST6, and BCAR1) were genome-wide significant for all three traits (migraine, headache, and T2D)." (PMID 36292730, 2022).
neuroblastoma (2 papers, 2023 to 2024). Neuroblastoma (NB) is the most common solid, extracranial childhood tumor. "Additionally, in neuroblastoma, CFDP1 overexpression has been reported to be associated with shorter OS (p = 9.7 × 10−9) and event-free survival (p = 5.2 × 10−7)." (PMID 38893126, 2024). "It has been recently reported that CFDP1 is also a neuroblastoma (NB) susceptibility gene." (PMID 37566073, 2023).
pancreatic carcinoma (2 papers, 2022 to 2023). "Research has shown that CFDP1 was identified as a new candidate pancreatic cancer susceptibility gene, and results demonstrated a remarkable reduction in overall survival among the patients with highsss expression." (PMID 35861040, 2023). "In clinically relevant disease studies, CFDP1 was identified as a new candidate pancreatic cancer susceptibility gene." (PMID 35861040, 2023). "Moreover, some studies have confirmed that CFDP1 is a risk gene for pancreatic carcinoma." (PMID 35449571, 2022).
Arrhythmia (1 paper, 2023). Any cardiac rhythm other than the normal sinus rhythm. "The detected phenotype of bradycardia and arrhythmias is an observation with potential clinical relevance for humans carrying heterozygous CFDP1 mutations and their risk of developing CAD." (PMID 37566073, 2023).
artery disease (1 paper, 2023). "Researchers found CFDP1 (along with YAP1 and STAT6) for HCAECs that passed the 5% false discovery level (FDR) correction at the gene level which associates CFDP1 with artery disease traits." (PMID 37566073, 2023).
asthma (1 paper, 2022). "Of the lung function candidate genes, rare variant burden in four genes (MAPT, CFDP1, EML3, and LTBP4) was nominally associated with asthma risk in our study." (PMID 35368043, 2022).
autoimmune disease (1 paper, 2020). A disorder resulting from loss of function or tissue destruction of an organ or multiple organs, arising from humoral or cellular immune responses of the individual to their own tissue constituents. "Three AMD-associated genes (BCAR1, CFDP1, and TMEM170A) residing within a locus on chromosome 16 (chr16:75233867-75516739), coincide with GWAS signals of six different trait groups, namely “organ function”, “cancer”, “neurological diseases”, “autoimmune diseases”, “metabolic traits”, and “AMD”." (PMID 32005911, 2020).
congenital heart disease (1 paper, 2023). A heart disease that is present at birth. "It is possible that the common origin of neural crest cell identity for coronary arteries, sympathetic ganglia and adrenal medulla might underlie the role of CFDP1 in both NB and CAD, as well as in different congenital heart diseases." (PMID 37566073, 2023).
gastric adenocarcinoma (1 paper, 2023). "The findings demonstrated that CFDP1 can independently serve as a prognosticator of survival among patients with gastric adenocarcinoma, which could offer a conceptual framework for targeted therapy of patients after surgery." (PMID 35861040, 2023).
liver cancer (1 paper, 2023). An epithelial or non-epithelial malignant neoplasm that arises from the liver. "We performed a sequence of experiments (in vivo and in vitro) for the purpose of investigating the specific function of CFDP1 in liver cancer." (PMID 35861040, 2023). "Meanwhile, CFDP1 can promote the malignant development of liver cancer in vivo and in vitro." (PMID 35861040, 2023). "We injected the luciferase‐expressing and stably transfected liver cancer cells into BALB/C nude mice via tail vein to further investigate whether CFDP1 affects the metastasis of liver cancer (in vivo)." (PMID 35861040, 2023).
microcephaly (1 paper, 2017). A congenital or acquired developmental disorder in which the circumference of the head is smaller than normal for the person's age and sex. "In any case, in view of the similarities with MCPH1, it would be interesting to include Cfdp1 gene in the sequencing panels for microcephaly and related human disorders." (PMID 28367969, 2017).
psoriasis (1 paper, 2022). An autoimmune condition characterized by red, well-delineated plaques with silvery scales that are usually on the extensor surfaces and scalp. "However, there is not enough evidence for CFDP1, TRAPPC9, HSD17B7, and KIAA0415’s effects on psoriasis and neutrophils." (PMID 36569916, 2022).
Williams-Beuren syndrome (1 paper, 2025). "DDX3XWT-specific interactor CFDP1 (Craniofacial Development Protein 1) is associated with cell cycle progression and the neurodevelopmental disorder Williams-Beuren syndrome." (PMID 39836689, 2025).
cancer (4 papers, 2020 to 2024). A tumor composed of atypical neoplastic, often pleomorphic cells that invade other tissues. "The majority of these Cfdp1 alterations are associated with uterine endometrial carcinomas, suggesting that Cfdp1, and likely the SRCAP remodeler, are key for suppressing cancer initiation or progression in this cell type." (PMID 38809771, 2024). "Co-culture of melanoma cells with endothelial cells composing the abluminal surface of blood vessels, was demonstrated to induce the expression of genes linked to cancer cell migration (CCL2, ICAM1), cancer progression (TRAF1, SERPINB2) or stem cell properties (PDGFB; CFDP1)." (PMID 34604096, 2021).
tumor (1 paper, 2023). "However, further investigations are necessary so as to further investigate the mechanism associated with CFDP1 that results in HCC tumor genesis and development." (PMID 35861040, 2023). "Thus, a novel mechanism involving CFDP1 and associated with tumor progression was identified." (PMID 35861040, 2023). "The overexpression of CFDP1 in tumor and adjoining normal samples of HCC patients and HCC cell lines was also observed." (PMID 35861040, 2023). "Then, the relation between CFDP1 and survival and tumor stage was analyzed using the GEPIA database, an online bioinformatics tool." (PMID 35861040, 2023). "Analysis of the findings revealed that large tumor size, increased extent of microvascular invasion, and high TNM and Edmondson stages could be attributed to high levels of CFDP1." (PMID 35861040, 2023). "To determine whether CFDP1 is significantly overexpressed in HCC samples, we used the qRT‐PCR technique to detect the relative mRNA levels of CFDP1 in 60 HCC pairs and the corresponding adjoining non‐tumor samples." (PMID 35861040, 2023).
CFDP1 also shares sentences with these, for which no sentence is quoted: atherosclerosis (1 paper); Bradycardia (1); cardiac arrhythmias (1); cystic fibrosis (1); fibroblastic disorder (1); Headache (1); neurodevelopmental disorder (1); neurological diseases (1); Obesity (1).